CCND1 (cyclin D1)
Diseases named in the same sentence as CCND1 in open-access papers (continued):
Sharing a sentence is not in itself a finding about the gene and the disease.
tumor (continued). "To determine whether the expression of clock-controlled genes was impaired in CRLM and the primary tumor, we analyzed mRNA expression of 2 circadian output genes (Cyclin-D1, and WEE-1)." (PMID 27492458, 2016). "Coordination of c-Myc with cyclin D1 or its upstream activators not only accelerates tumor formation, but also may drive tumor progression to a more aggressive phenotype." (PMID 27506388, 2016). "Cyclin D1 (Ccnd1) together with its binding partner Cdk4 act as a transcriptional regulator to control cell proliferation and migration, and abnormal Ccnd1·Cdk4 expression promotes tumour growth and metastasis." (PMID 27181366, 2016). "Since the membrane attachment of Ccnd1 was able to appreciably improve the invasiveness of tumor cells, we tested whether the improvement in invasion was RalB-dependent." (PMID 27105504, 2016). "Interestingly, the IRS values of Cyclin D1 and Ki67 staining at day 35 revealed a similar trend to the tumor incidence and miR-16 expression levels in colon epithelial cells." (PMID 26440311, 2015). "Coordination of c-Myc with cyclin D1 or its upstream activators may not only accelerate tumor formation but also drive tumor progression to a more aggressive phenotype." (PMID 26167492, 2015). "PAK7 up-regulates the cyclin D1 expression and promotes tumor cell proliferation." (PMID 26231038, 2015). "Finally, in vitro investigation confirmed that miR-211 is a tumor suppressor that controls Cyclin D1 and CDK6 expression." (PMID 25889927, 2015). "The multivariate analysis revealed that only the TNM stage and SUVmax were independently associated with survival (P < 0.05), whereas tumor size, nodal metastasis, the ratio of metastasized nodes to retrieved nodes, and CCND1 were not." (PMID 26689966, 2015). "Recently it has been reported that cyclin D1 involve in tumor progression and metastasis." (PMID 25823925, 2015). "Down-regulated let-7 has been identified in many types of tumours, suggesting a feedback loop may exist between let-7 and cyclin D1." (PMID 25702703, 2015). "Additionally, downregulation of CCND1 (p = 0.0234) expression to a minimum correlated with tumor-invasion into veins." (PMID 26008974, 2015). "PTEN is a tumor suppressing gene with many cancer-related biological functions such as inhibition of cell proliferation and migration and nuclear localization of Cyclin D1." (PMID 26770191, 2015). "Similarly, tumor-related signatures, like Cyclin D1, HOXA9, BMI1 and PDGF were enriched for the deregulated genes." (PMID 26113842, 2015). "Isogenic cell lines were engineered to overexpress either cyclin D1a (in Ccnd1+/+ MAFs +/+-D1a) or cyclin D1b (in Ccnd1KI/KI MAFs- KI/KI-D1b) (Fig3E), subcutaneously implanted into the flanks of nude mice, and monitored for tumor growth over a period of 1 year." (PMID 25787974, 2015). "The data suggested that indeed S3I-201 could decrease p-STAT3 and its target gene Cyclin D1 and Bcl2 effectively in vivo, which indicate the decrease of tumor size of nude mice using S3I-201 is an on-target effect." (PMID 26556875, 2015). "Such tumors rely on kinase activity of cyclin D1, and tumor growth could be abrogated not only by inactivation of cyclin D1 but also by CDK4/6 inhibition." (PMID 25940700, 2015). "Also consistent with the CGP results is lapatinib’s (row-clade d) sensitivity to tumor cells with ERBB2_MUT (column-clade E), which, according to these results, is also accompanied by MUTs in CCND1, NF2 and SMAD4." (PMID 26132924, 2015).
tumor (continued). "The amplified genes with overexpression in each tumor sample groups might be the potential therapeutic targets for the specific tumor type, such as CCND1, CCNE2 for the ER group and E2F5, EIF2C2 for the PR group." (PMID 26273658, 2015). "That seven of 10 cases with high-level amplification had a homogeneous FISH result suggests that CCND1 amplification might often represent an early event during tumor development." (PMID 25649416, 2015). "Although cyclin D1 could be responsible for the anti-tumor effect of XPO1 inhibition, it is known that the overexpression of cyclin D1 itself is not sufficient for development of MCL." (PMID 26340096, 2015). "This subgroup exhibited high-level amplification in CCND1 as well as alterations in several key cell cycle-related genes, which may be the drivers for the development of this tumor subtype and play a role in its aggressiveness." (PMID 25764003, 2015). "PMLs and tumor samples showed increased cyclin D1 mRNA levels compared to normal oral mucosa." (PMID 25645517, 2015). "To determine whether EVO affected cyclin D1 protein levels and apoptosis of tumor cells in vivo, we further analyzed cyclin D1 expression and tumor cell apoptosis in xenograft tumors using IHC and TUNEL staining, respectively." (PMID 26207989, 2015). "Furthermore, the overexpression of CDX2 upregulated the expression of Bax and downregulated the expression levels of survivin, Bcl-2, cyclin D1, Skp2 and c-Myc in the tumor tissues." (PMID 25738600, 2015). "By immunohistochemistry, we have revealed a significant increase in the expression of β-catenin and two known downstream targets of Wnt/β-catenin pathway cyclin D1 (CCND1) and Axin2 in the tumor tissues of the ApcMin/+;Slit2 and DMH/DSS-Slit2 mice, as opposed to their respective controls." (PMID 25605242, 2015). "As Cyclin D1 is a downstream target of Wnt/β-catenin pathway and plays a key role as a regulator of cell proliferation, these data suggest that PRMT5 might mediate HCC tumor proliferation and development by regulating Cyclin D1 through Wnt/β-catenin pathway." (PMID 26541651, 2015). "Cyclin D1, which is regulated by β-catenin, contributes to tumor progression." (PMID 26219398, 2015). "However, the duration of complete responses has been shown to be shorter for this group of tumors than for other types of MM, possibly due to the higher rates of proliferation of cyclin D1-expressing tumor cells." (PMID 25881299, 2015). "Furthermore, bardoxolone methyl reduced cyclin D1 levels in tumors from xenograft and transgenic mouse models, and in tumor biopsies from patients enrolled in a phase 1 clinical trial (ClinicalTrials.gov ID: NCT00529438)." (PMID 25897966, 2015). "Among other malignancies with cyclin D1 locus alterations, there is little evidence of association with tumor progression." (PMID 25787974, 2015). "Moreover, HNF1A-AS1 was determined to promote tumor proliferation and metastasis, both in vitro and in vivo, by regulating cyclin D1, E-cadherin, N-cadherin and β-catenin expression." (PMID 25863539, 2015). "Overexpression of cyclin D1 may be an early event in hepato-carcinogenesis, and it plays a role in tumor growth and differentiation." (PMID 25605484, 2015). "In subjects exposed to etodolac with pre- and postexposure flash frozen tumor available (n = 15), we evaluated the gene expression levels associated with the COX-2 pathway (COX-2 and β-catenin) and the RXRα pathway (RXRα, PPARγ, and cyclin D1)." (PMID 26275572, 2015). "Cyclin D1 staining showed that they are composed of tumor cells with little plasma." (PMID 25859411, 2015). "In vivo, cyclin D1 protein expression in tumor tissues was also greatly up-regulated." (PMID 24797571, 2014).
tumor (continued). "In order to investigate whether SFRP2 affects the growth of OSCC via the Wnt signaling pathway in nude mice, the expression levels of GSK-3β, β-catenin and cyclin D1 in tumor tissues were further analyzed by immunohistochemical analysis." (PMID 25189527, 2014). "This notion was reinforced when tumor cells expressing wild-type Rb were found to have genetic and epigenetic alterations of the p16 tumor suppressor gene or oncogenic expression of cyclin D1, D2, D3, Cdk4, and Cdk6 genes, which became known as the ‘p16-cyclin D-Rb’ pathway." (PMID 24876129, 2014). "For cancers located in the colon, contrasting associations were found, with an increased risk of lymph node-positive and non-metastatic tumours, as well as for cyclin D1 positive tumours." (PMID 24885829, 2014). "High expression of vascular endothelial growth factor (VEGF), moderate or high expression of c-Myc and cyclin D1 were observed in tumor sections at different stages (2, 4, 6 and 8 weeks after cancer being found) when compared with that of the normal mammary glands." (PMID 25230850, 2014). "ShCCND1 inhibited the expression of cyclin D1 and inhibited tumor cell growth in vitro." (PMID 24618206, 2014). "Of interest, cyclin D1 protein expression in tumor tissues was markedly up-regulated by MVs." (PMID 24797571, 2014). "The authors also observed that levels of ErbB2, pErbB2, and cyclin D1 increased in a time-dependent manner in the mammary glands in BRCA1-deficient mice, and CDDO-Me inhibited the constitutive phosphorylation of ErbB2 in tumor tissues from these mice." (PMID 24552536, 2014). "Next, we examined how treatment of sgRNA targeting cyclin D1 affects tumor cell numbers." (PMID 25437003, 2014). "Moreover, let-7b also acts tumor-suppressing functions by targeting the cell cycle molecules(Cyclin D1 and D3), c-Myc and ER-α." (PMID 24810113, 2014). "Furthermore, we found a 4.1-fold decrease of cyclin D1-positive cells in tumor sections from RocA-treated mice relative to that in vehicle-treated mice (right and 6G, lower)." (PMID 24568222, 2014). "The MIF and cyclin D1 proteins appeared to be located in the cytoplasm of tumor cells." (PMID 25015194, 2014). "By contrast, the protein expression level of COX2 and cyclin-D1 increased as the tumor malignancy progressed, suggesting that SOX7 may function through the Wnt/β-catenin signaling pathway as a tumor suppressor." (PMID 25297608, 2014). "In addition, MIF expression positively correlated with cyclin D1 expression in HCC tissues and was closely associated with HCC tumor size." (PMID 25015194, 2014). "Similarly to pRb inactivation, induced cyclin D1 overexpression in already established dysplasia would allow to accelerate tumor formation and proliferation." (PMID 24419005, 2014). "Changes of CCND1 gene expression have been reported in several neoplasias." (PMID 24605326, 2014). "In our previous studies, we identified that OPN may interact with CD44 to induce CD44 cleavage, possibly through increased expression of both β-catenin and cyclin D1 in GIST tumor tissues." (PMID 24947165, 2014). "Our preliminary exploration of the mechanisms that LOC401317 utilizes as a tumor suppressor shows that LOC401317 may cause cell cycle arrest by increasing p21 expression and decreasing cyclin D1 and cyclin E1 expression." (PMID 25422887, 2014). "The results of western blotting showed that the expression of β-catenin and cyclin-D1 that is β-catenin target molecule was simultaneously down-regulated in tumor tissues of mice treated with hUCMSCs-LV-IL-21 in comparison with the control group, hUCMSCs group and hUCMSCs-LV-Vec group." (PMID 24444073, 2014). "In addition, miR-206 suppresses CCND1 expression and plays a tumor suppressive function in skeletal muscle differentiation." (PMID 25304455, 2014).
tumor (continued). "Therefore, the distribution of cyclin D1 in the various tumor subtypes was consistently found to be correlated with ERα status." (PMID 24559156, 2014). "The ratio of cyclin D1 positive cells statistically increased with the tumor grade." (PMID 25322986, 2014). "The results of the present study indicate that cancer cells with a high expression of cyclin D1 and with drug resistance may survive, even if certain tumour cells of primary foci die and local control occurs as the result of pre-operative adjuvant therapy." (PMID 24944679, 2014). "The stability of both c-fos and cyclin D1 mRNAs in BCT may results from the stabilization of tumor cells by the stabilizing reagent present in the BCT." (PMID 24602297, 2014). "Hyper-activation of cyclins, especially the G1/S administrator cyclin D1 may favor tumor development by inducing unscheduled cell division in progenitor cells." (PMID 25477004, 2014). "Furthermore, overexpression of SOX7 suppressed tumor formation with down-regulation of cyclin D1 and c-myc in vivo." (PMID 24816720, 2014). "We hypothesize that ENO1 may contribute to tumor progression via the PI3K/Akt pathway mediating the activity of Cyclin D1, Cyclin E, and NF-κB, which will eventually result in hyperphosphorylation of Rb and downregulation of E-cadherin mediated classical EMT." (PMID 24650096, 2014). "Furthermore, metformin treatment also markedly reduced the expression of cyclin D1 and p-mTOR, which was confirmed by the scoring of percentage positive cells under 400× magnification in ten randomly selected areas in each tumor sample." (PMID 24351837, 2013). "These important observations not only support previous findings that Cyclin D1 and Bcl-2 are target genes silenced by miR-195 but also demonstrate that the expression of miR-195 is potentially a more accurate prognostic tumor marker than Cyclin D1 or Bcl-2 levels alone in TSCC patients." (PMID 23451060, 2013). "However, it is also possible that the combined effects of many tumor-promoting HRGs, including VEGF and Cyclin D1, were responsible for the tumor-inducing power of HIF." (PMID 24260413, 2013). "The overexpression of neither VEGF nor CCND1 in VHL+/+ 786-O cells was able to cause robust tumor growth (data not shown)." (PMID 24260413, 2013). "Immunohistochemical staining of the xenograft tumors demonstrated that β-catenin, E-cadherin, and Cyclin D1, the target of Wnt signaling, were strongly up-regulated in tumor segregants (TSs) derived from HONE1 hybrids, as compared with control tumors from the parental HONE1 and MCH4.5-2TS cells." (PMID 24073846, 2013). "Furthermore, cyclin D1 knockdown in combination with cisplatin treatment inhibited tumor cell growth more effectively than single treatments." (PMID 23806108, 2013). "Interestingly, several studies have also reported correlations between cyclin D1 overexpression and poor clinical prognostic characteristics, including advanced tumor stage, tumor recurrence, and metastatic spread in papillary thyroid." (PMID 23591524, 2013). "Thus, we investigated the effects of cyclins, in particular cyclin D1, downstream of TGFβ-mediated tumor progression." (PMID 23786849, 2013). "It has been reported that aberrant STAT3 activation promotes uncontrolled tumor cell growth and survival through multiple mechanisms, including increased expression of oncogenes, such as c-myc, Skp2, and cyclin D1, as well as antiapoptotic proteins, including Bcl-2, Bcl-xL, Mcl-1, and survivin." (PMID 24386318, 2013).
tumor (continued). "The anti-tumor effect of miR-195 in TSCC could be at least partially via inhibition of Cyclin D1 and Bcl-2 expression." (PMID 23451060, 2013). "The tumor classification and cyclin D1 were able to act as independent prognostic factors." (PMID 24223635, 2013). "This indicates that cyclin D1 is relevant to tumor stage and may be regarded as a potential prognostic signal of head and neck SCC." (PMID 24223635, 2013). "Additionally, cytoplasmic cyclin D1 and c-myc were less prominent in the tumour tissue from the ASO-miR129-5p-treated cells group than in tumours from the GFP-lentivirus group or untreated group." (PMID 24194897, 2013). "The tumor classification and cyclin D1 each were able to act as independent prognostic factors." (PMID 24223635, 2013). "Furthermore, ectopic expression of Ccnd1 is sufficient to promote tumor formation by mediating growth factor independence and forces quiescent cells to reenter the cell cycle." (PMID 23967156, 2013). "Regulation of the cyclin D1 protein level is one of the critical aspects in cell proliferation and tumor development, indicating that cyclin D1 may be regarded as a therapeutic target in cancer." (PMID 24499623, 2013). "However, cyclin D1 expression in RCCs inversely correlated with advanced tumor stage, and moderate to high expression of cyclin D1 in RCCs independently predicted improved postoperative prognosis, with an HR of 0.13 (95% CI, 0.02–0.96)." (PMID 24137339, 2013). "Thus, our findings highlight the cyclin D1/p21 signaling axis as a critical regulator of TGFβ-mediated tumor growth initiation and local tumor cell invasion, both in vitro and in vivo." (PMID 23786849, 2013). "Quantification and statistical analysis showed, compared to control and γ radiation, significantly higher levels of cyclin D1 in tumor-free (p<0.0004 compared to control and γ radiation) as well as in tumor-bearing (p<00006 compared to control and γ radiation) areas after 56Fe radiation." (PMID 23555653, 2013). "Moreover, Trop-2 plays a significant role in the regulation of tumor proliferation by increasing the stability of cyclin D1 or activating the signal pathway of ERKl-MAPK." (PMID 24137332, 2013). "The majority of cases (89.3%) were cyclin D1-positive (>5% staining of tumor cells)." (PMID 23420289, 2013). "Taken together, the present study indicates that LPLUNC1 delays NPC cell growth by inhibiting the MAPK and cyclin D1/E2F pathways and suggests that LPLUNC1 may represent a promising candidate tumor suppressor gene associated with NPC." (PMID 23650533, 2013). "However, immunostaining intensities of cyclin D1 in the cancer cells was inversely correlated with advanced tumor stage (P=0.046; Spearman’s correlation coefficient, −0.211)." (PMID 24137339, 2013). "Using multi-factor Cox proportional hazards regression models to analyze TNM stage, lymph metastasis, tumor classification, tumor location, cyclin D1 and Ang-2, it was demonstrated that the tumor classification and cyclin D1 are associated with the survival rate." (PMID 24223635, 2013). "For those tumours that were cyclin D1-positive (n = 14), only 43% (n = 6) were positive for p16." (PMID 23672832, 2013). "Using log-rank one-way analysis, we demonstrated that laryngeal SCC prognosis is associated with smoking, TNM stage, lymph metastasis, tumor classification, tumor location, cyclin D1 and Ang-2, but is not correlated with age, gender or drinking habit." (PMID 24223635, 2013). "Cyclin D1 has been recognized as a promising biomarker for predicting tumor behavior." (PMID 24222746, 2013). "Moreover, MiR-378 promotes cellular transformation, at least in part, by targeting and inhibiting TOB2, which is further elucidated as a candidate tumor suppressor to transcriptionally repress proto-oncogene cyclin D1." (PMID 24147003, 2013). "Direct inhibition of cyclin D1 in tumour cells by Resv has been previously reported." (PMID 23527233, 2013).